UTP23 (UTP23 small subunit processome component)
Description:
Involved in rRNA-processing and ribosome biogenesis.
Synonyms: C8orf53; MGC14595
Tractability: PROTAC: UniProt records ubiquitination sites on it; ubiquitination databases record sites on it; its protein half-life has been measured.
Gene: Protein-coding gene on chromosome 8 (116,766,505 to 116,849,463, forward strand). Ensembl gene ENSG00000147679.
Subcellular location: Nucleus, nucleolus
Subcellular location (Human Protein Atlas): Nucleoli
Gene Ontology:
Molecular function: mRNA 3'-UTR binding; mRNA 5'-UTR binding; protein binding; RNA binding; small ribosomal subunit rRNA binding
Cellular component: small-subunit processome; nucleolus
Genetic constraint (gnomAD): Loss-of-function variants: 12 observed, 21.98 expected, observed/expected ratio (o/e) 0.55, 90% interval 0.35 to 0.88. The upper end of that interval is the gene's LOEUF score, 0.88, which puts it in group 3 of 6, group 1 being the genes least tolerant of losing a copy. Missense variants: 282 observed, 299 expected, observed/expected ratio (o/e) 0.94, 90% interval 0.86 to 1.04. Synonymous variants: 108 observed, 103.56 expected, observed/expected ratio (o/e) 1.04, 90% interval 0.89 to 1.22.
Homologues: Orthologues: chimpanzee UTP23 (99% identical), macaque UTP23 (97% identical), dog UTP23 (94% identical), rabbit UTP23 (92% identical), pig UTP23 (91% identical), guinea pig UTP23 (88% identical), mouse Utp23 (87% identical), rat Utp23 (80% identical), tropical clawed frog utp23 (63% identical), zebrafish utp23 (57% identical), Drosophila melanogaster CG17652 (38% identical), Caenorhabditis elegans C34E10.10 (38% identical). Paralogues in human: FCF1 (19% identical).
Diseases named in the same sentence as UTP23 in open-access papers:
UTP23 is named in the same sentence as 6 diseases in open-access papers, as found by Europe PMC text mining. Sharing a sentence is not in itself a finding about the gene and the disease. The quoted sentences say what the papers report.
ovarian carcinoma (2 papers, 2022 to 2023). A malignant neoplasm originating from the surface ovarian epithelium. "Reduced UTP23 expression has been associated with poor prognosis in patients with ovarian cancer possibly by affecting sensitivity to paclitaxel-based chemotherapy." (PMID 38665548, 2023). "Expression of UTP23, NUDT13 and CPNE7 are associated with poor prognosis in tumors including ovarian cancer, gastric cancer, oral squamous cell carcinoma." (PMID 36685828, 2022).
colorectal cancer (1 paper, 2020). A primary or metastatic malignant neoplasm that affects the colon or rectum. "Interestingly, seven of the shared significant genes have been associated to colorectal cancers, including UTP23, GREM1, SCG5, SMAD7, CABLES2, LAMA5, and PREX1." (PMID 32245788, 2020).
tumor (3 papers, 2015 to 2024). "We further explored if rs1129406 (ATF1, 12q13), rs12303082 (FAM186A, 12q13), rs6580742 (FAM186A, 12q13), rs16888728 (UTP23, 8q24) and rs3184504 (SH2B3, 12q24) genotypes affect the CRC risk differentially by sex, age at diagnosis, tumor site, stage and MSI status." (PMID 26553438, 2015). "According to the expression levels and regression coefficients, the downregulated BAX, PWP2, SERTAD1, S1PR4, ZFAND1, NUDT13 and ZNF107 with HR < 1 were considered as tumor suppressors, whereas the MVD, BAD, CPNE7, CPNE7, UTP23 and ZNF124 upregulated with HR > 1 were regarded as oncogenes." (PMID 36685828, 2022).
cancer (2 papers, 2020 to 2022). A tumor composed of atypical neoplastic, often pleomorphic cells that invade other tissues. "The expression plots between signature ARMC1 and signature UTP23 show that they are associated with each other, and that they are co-amplified in 76.2% of the cancer cases." (PMID 33057153, 2020). "The amplified region contains co-localized PAN cancer gene signatures of UTP23 and SHARPIN gene signatures, and it has enabled the clustering of 21 human cancer types into seven cross-cancer gene signatures based on coregulated genes." (PMID 36497066, 2022). "On the other hand, the expression levels of signature UTP23 and signature SHARPIN are independent although these two signatures are co-amplified in 77.6% of the cancer cases." (PMID 33057153, 2020).
UTP23 also shares sentences with these, for which no sentence is quoted: gastric cancer (1 paper); oral squamous cell carcinoma (1).